BRCA2 (BRCA2 DNA repair associated)
Diseases named in the same sentence as BRCA2 in open-access papers (continued):
Sharing a sentence is not in itself a finding about the gene and the disease.
cancer (continued). "A recent systematic review identified ATM, BRCA1, BRCA2, CDKN2A, CHEK2, and PALB2 as the most frequent genes harboring GPV in individuals with PDAC not meeting criteria for any cancer predisposition syndrome with varying degrees of family history." (PMID 35805029, 2022). "Lack of family history does not imply significantly lower cancer risks, and lifetime risk of developing cancer was 83%, 76% for BRCA1, BRCA2 carriers identified by screening, respectively, not significantly different than risks to carriers with family history." (PMID 36551598, 2022). "The effect is greatest for BRCA2 mutations, probably because women with BRCA1 mutation more often develop estrogen and progesterone negative cancers." (PMID 33996049, 2021). "We identified 99 unique FANCI variants (VAF < 1%) in 516 AUS HGSC BRCA1 and BRCA2 pathogenic variant negative cases and 4878 AUS cancer-free controls from available WES data." (PMID 34861889, 2021). "Cancer cell lines lacking BRCA1 or BRCA2 functions demonstrated selective sensitivity to quinacrine, mitoxantrone, and doxorubicin." (PMID 33784323, 2021). "The lack of a definitive in vitro or in vivo model for the cancer-promoting activity of BRCA2 poses an issue when one considers the evaluation of germline VUS to predict future cancer risk." (PMID 34065235, 2021). "Genetic studies of the FC population have helped validate the role of rare potentially PVs in BRCA1 and BRCA2 in cancer syndrome families, sporadic cancer cases regardless of family history of cancer, and the general population." (PMID 34298626, 2021). "Further, our identified role for PolQ in mitosis is relevant to human cancer, as cancer cells lacking the BRCA2 or RAD52 repair proteins rely heavily on PolQ-mediated alt-EJ repair in mitosis." (PMID 34946831, 2021). "Representing a complex and heterogeneous type of cancer, its occurrence is attributed by both genetic (gene mutations, e.g., BRCA1, BRCA2) and non-genetic (race, ethnicity, etc.)risk factors." (PMID 34199484, 2021). "We presumed that high ATF1 expression confers resistance to PARP inhibitors in cancer cells with HRD because of the alteration of non-BRCA1 HR factors, such as BRCA2, in which sufficient ATF1 and intact BRCA1 could stimulate ATF1-mediated transactivation." (PMID 36860287, 2021). "Generally, patients with pathological BRCA mutations present the best benefit from PARPi therapy, but clinical studies demonstrated the efficacy of PARPis against cancers presenting defects in HR due to other genes, such as ATM and partner and localizer of BRCA2 (PALB2)." (PMID 34439854, 2021). "Up to 45% of cancer patients with an HRD tumor according to CHORD do not have an event in BRCA1 or BRCA2." (PMID 34067105, 2021). "We previously reported a rare BRCA1 and BRCA2 pathogenic variant negative OC family (F1528) in a study of the histopathology of OC and BRCA1 and BRCA2 pathogenic variant carrier status of FC cancer families." (PMID 34861889, 2021). "In addition, the repurposed cancer types for category L drugs are mostly enriched as the BRCA_OV, which are related to the mutant genes BRCA1 and BRCA2." (PMID 33627666, 2021). "These OC or BC cases were selected based on their family history of OC or BC, or regardless of cancer family history (sporadic cases), where BRCA1 and BRCA2 pathogenic variant carrier status was known." (PMID 34861889, 2021). "Finally, we show that CAM833 inhibits the cellular response to DNA damage, potentiating in BRCA2 wild-type cells the cytotoxic effects both of ionizing radiation or of PARP1 inhibitors, opening future avenues for anti-cancer drug development." (PMID 33662256, 2021).
cancer (continued). "Surprisingly, BRCA1, RAD51, or RAD51C depletion, unlike BRCA2 depletion, cannot lead to synthetic lethality upon concomitant loss of MUS81 in cancer cells." (PMID 33791310, 2021). "There were 12 patients with germline mutations in cancer predisposition genes that are not currently associated with RMS, including two genes with heterozygous mutations in more than one patient: BRCA2 (n = 6) and SDHA (n = 2)." (PMID 34065162, 2021). "Olaparib is a clinically used PARP1-i chemotherapeutic agent that is especially effective for treatments of BRCA1 or BRCA2 negative cancers, such as ovarian and breast cancer types." (PMID 33926008, 2021). "A recent search for new BRCA2 partners identified HSF2BP (also named MEILB2) as another BRCA2-binding protein, endogenously expressed in meiotic cells, and ectopically produced in cancer cells." (PMID 34356684, 2021). "Thus, chemical inhibition of the protein-protein interaction between BRCA2 and RAD51 disrupts HDR and potentiates DNA damage-induced cell death, with implications for cancer therapy." (PMID 33662256, 2021). "Twelve patients (3.7%) had a second primary cancer, with breast being the most common second cancer in BRCA2 carriers (41.7% vs. none in BRCA1 carriers, P = 0.007)." (PMID 34575694, 2021). "Previous review of their histopathology reports indicated ductal/carcinoma of no special type in all five BRCA2 c.7934delG carriers." (PMID 34660253, 2021). "Even if they are not clearly BRCA2 related carcinomas, esophageal and throat cancers were detected in 4 individuals from 3 different families (BC6, BC17, and BC225) suggesting an upper aero digestive cancer predisposition." (PMID 34456966, 2021). "Six of the eight patients reported a family history of BC and other malignancies, whereas the patients carrying a BRCA1 exon 21 deletion and a complete BRCA2 deletion were not aware of any cancers in the family." (PMID 32375709, 2020). "The carriers of more than one pathogenic variant in different cancer predisposing genes, BRCA1 and BRCA2 as an example, has been described but reports are not common." (PMID 32726901, 2020). "This study found a 0.2% allele frequency for BRCA1, BRCA2, and PALB2 founder variants in controls with no personal or family history of cancer." (PMID 32300229, 2020). "In a pan-cancer analysis of BRCA1 and BRCA2 genomic alterations using hybrid captured-based comprehensive genomic profiling, the fraction of BRCA1/2 altered biallelic cases was 68.7%, which is highly associated with elevated genome-wide loss of heterozygosity (gLOH)." (PMID 33324554, 2020). "However, in BRCA wilde-type cancers, an inverse correlation between the expression of BRCA1/2-mRNA and miR-34 b/c and between miR-34a and BRCA2 mRNA was pointed out." (PMID 32047551, 2020). "Contrary to BRCA2 that promotes Rad51-dependent recombination, gene amplifications rather than mutations have been observed for RAD52 in cancer cells." (PMID 32355220, 2020). "In relation to the age of cancer onset, in DM patient with PAC we did not observe a younger age compared with carriers of a single BRCA2 mutation." (PMID 33287145, 2020). "Interestingly, PLKO.1‐POU6F2 transfection significantly changed the expression of some cancer resistance‐related gene (P‐gp, MRP2 and BRCA2) in this study (P < .001)." (PMID 32100443, 2020).
cancer (continued). "Although we observed a predominance (23.2%) of BRCA1/BRCA2 variants in patients with HGSOC, these alterations were not exclusively associated with this group, as they were also frequently found in carcinomas with other histologies (10%)." (PMID 32850417, 2020). "PTEN, BRCA1, BRCA2, PI3K, and CCND1 genes were related to the BREAST cancer signaling pathway." (PMID 30792708, 2019). "In this study, the expression of BRCA2 was up-regulated, while CCND1 protein was down-regulated, which indicated that the infection might inhibit the growth of BREAST cancer." (PMID 30792708, 2019). "Suppression of BRCA2 expression by siRNA or shRNA increased the sensitivity to 6-TG- and olaparib-induced apoptosis but did not affect cancer cell response to taxane." (PMID 31284411, 2019). "Although not lethal, BRCA2 inactivation in cancer-derived human cells significantly slows down cell proliferation." (PMID 31316060, 2019). "Furthermore, a study evaluating the coding regions and exon-intron boundaries of a 42-cancer gene sequencing panel (including BRCA1 and BRCA2) identified one or more VUS in approximately 90% of the patients." (PMID 30696104, 2019). "Future examination of R-loops in cancer models should determine whether the seemingly independent functions of BRCA1 and BRCA2 are coordinated to prevent RF collapse through FANC-complex-mediated mechanisms." (PMID 31225499, 2019). "Notably, in a recent study using a low detection limit, Peplonska and colleagues detected evidence of WBC BRCA2 and BRCA1 methylation in 18.3% and 21.5%, respectively, among (presumably) cancer-free participants." (PMID 31225507, 2019). "LOH is observed in most cancers in BRCA1, BRCA2, and NBN carriers." (PMID 31614901, 2019). "Recent studies demonstrated that RAD52 has an important role in genomic stability maintenance and cancer suppression in mammalian cells, while several HR proteins including BRCA1, BRCA2, PALB2, and RAD51 paralogs (RAD51B, C, D, and XRCC 2 and 3) present an inactivated and depleted activity." (PMID 31652722, 2019). "Cancer cells lacking functional BRCA2 are defective in protecting nascent DNA from degradation at stalled replication forks and cannot properly repair the DSBs that result from forks collapse." (PMID 31529615, 2019). "We should emphasize that until 2016, genetic studies regarding HBOC were practically limited to the BRCA1/BRCA2 genes, mainly due to the high cost of Sanger and MLPA sequencing techniques, but at present, most Familiar Cancer Units use gene panels related to HBOC." (PMID 29884136, 2018). "Five of the pan-cancer ALFRED genes (BRCA1, ATM, BRCA2, NSD1, and TPCN2) were individually significantly enriched for RDGVs in cases versus controls (P < 0.05 by pan-cancer case-control analysis) with one additional gene, NIPAL3, marginally significant (P = 0.07 by case-control analysis)." (PMID 29973584, 2018). "In many cancer centres, immediate or post-chemotherapy bilateral mastectomy has become an almost routine recommendation for BRCA1 and BRCA2 mutation carriers regardless of the size or focality of the presenting tumour." (PMID 29337092, 2018). "First, there was a delay in testing and counselling male individuals from BRCA1 families, since BRCA2 men seemed to be at higher cancer risks and there was no clear recommendation to test men." (PMID 29456621, 2018). "This hypothesis is supported by the signature of positive selection of some FA/BRCA components (BRCA2, FANCA, FANCE, and FANCL) identified in long-lived and cancer-resistant species." (PMID 30487452, 2018). "Most participants had not heard of genetic testing for cancer risk and those that had did not know about the specific BRCA1/BRCA2 genes." (PMID 30021754, 2018).
cancer (continued). "BRCA1-associated cancers are more likely to present specific characteristics like the absence of ER, PR, and HER2 receptors, unlike BRCA2-related cancers, which usually express ER and PR." (PMID 30249004, 2018). "It is clear from the genetic data that there are individuals present in the UK10K cohort who have cancer syndromes caused by deleterious mutations (such as BRCA1 nonsense, BRCA2 frameshift and APC frameshift variants)." (PMID 29641532, 2018). "Evidence suggests that promoter hypermethylation is not an obvious contributor to BRCA2 related cancers." (PMID 30453575, 2018). "Cancer cells lacking functional BRCA1 or BRCA2, critical players in HRR, were found to be particularly sensitive to PARP1 inhibition." (PMID 29684820, 2018). "The patient UPR1024, BRCA2 c.1794_1798del5 carrier, was diagnosed at 52 years of age and did not report any family history of cancer." (PMID 30400234, 2018). "For example, known disease genes BRCA2, CDH1, IDH1, CDKN2A, NME1 and FGFR3 frequently occurred at the top one in seven cancer types (including BC, GC, GBM, MB, MM, NB and OC), even though only two or three known-disease genes existed in NB, GBM and MB gene lists." (PMID 28076842, 2017). "In cancer cells lacking BRCA2, dysfunctional checkpoints, including SAC failure, enable mitotic entry and progression with incompletely replicated genomes." (PMID 28714477, 2017). "There was also a trend towards reduced TTP for patients with germline BRCA2 mutant cancers who developed RDR compared to germline BRCA2 mutant patients who did not have RDR (320 vs 494 days; p=0.045)." (PMID 29262651, 2017). "We identified no aberrant copy number changes in the HBOC cancer risk genes, including BRCA1 and BRCA2, by high resolution array CGH." (PMID 28435519, 2017). "Some of them were cancer-related according to COSMIC and HGMD databases (no founder mutations in BRCA1 and BRCA2 have been found)." (PMID 28787462, 2017). "Potential promotion of metastasis through interaction with BRCA2 and PRC2 in other cancer types." (PMID 27148353, 2016). "In most cell lines with intact DSB DNA repair mechanisms, treatment with PARP inhibitors at doses that successfully inhibit PARP activity does not cause cell death, providing an exquisite approach to specifically targeting cancer cells, especially those harboring mutant BRCA1 and BRCA2." (PMID 27705915, 2016). "The BRCA1/2 carriers (mean±standard deviation: 46.6±8.5 years), especially BRCA2 (46.2±8.0 years), had an earlier onset age than non-carriers (50.7±10.3 years), which supports BRCA genes as potential cancer risk factors." (PMID 27257965, 2016). "In the Bonome dataset (GSE26712), Adalnet selected only two not-isolated genes (RB1 and BRCA2) involved in two different cancer pathways." (PMID 27378931, 2016). "The Counsyl Inherited Cancer Screen we have developed employs next-generation sequencing and includes comprehensive analysis of all coding exons of BRCA1 and BRCA2, 20 bp of flanking intronic sequences, and selected intronic and untranslated regions with known pathogenic variants." (PMID 27375968, 2016). "We report that BRCA2 downregulation sensitized multiple human tumor cell lines (but not non-cancer human kidney cells) to olaparib and, combined with olaparib, increased aneuploidy and chromosomal translocations in human tumor cells." (PMID 26959114, 2016). "In other words, reduction of IDO and BRCA2 does not appear to sensitize cancer cells to a drug such as 5FUdR that targets TS." (PMID 26579709, 2015).
cancer (continued). "The expression of PARP1, BRCA1 and BRCA2 was not correlated with cancer patients' age, TNM Stage, and pathological pattern of cancer." (PMID 25865228, 2015). "The BRCA2 negative expression rate gradually decreased in the well− (60%; 6/10), moderately (46%; 22/48) and poorly (56%; 9/16) differentiated cancer tissues, however, the differences between results were not significant (P>0.05)." (PMID 25436004, 2015). "Many cancer sera showed OD values several fold above the cutoff, indicating that autoantibodies response to three TAAs (PARP, BRCA1 and BRCA2) in some cancer patients were quite robust and not just mildly elevated." (PMID 25865228, 2015). "Panels included comprehensive analysis of 14–22 cancer susceptibility genes (BRCA1 and BRCA2 not included), depending on the panel ordered (BreastNext, OvaNext, ColoNext, or CancerNext)." (PMID 24763289, 2014). "Rare exonic, non-truncating variants in known cancer susceptibility genes such as BRCA1 and BRCA2 are problematic for genetic counseling and clinical management of relevant families." (PMID 24489791, 2014). "The discovery of fusion transcripts containing partners that regulate repair of DNA double-strand breaks and homologous recombination, such as RAD21, RDM1, BRCA2 and SHFM1, is consistent with abundant evidence for aberrant regulation of DNA replication in cancer." (PMID 24727804, 2014). "BRCA1 tumors are typically estrogen receptor (ER) negative, progesterone receptor (PR) negative and HER2 negative (triple-negative) cancers, while the majority of BRCA2 tumors are ER positive and HER2 negative." (PMID 23704984, 2013). "More recently, PARP moved into the spotlight with the discovery that PARP inhibition in both cancer cell lines and human tumors lacking BRCA1 or BRCA2 is selectively cytotoxic compared to non-mutation containing tumors." (PMID 24098868, 2013). "In a phase I trial of the PARP inhibitor olaparib (formerly AZD2281), significant responses were observed only in BRCA1-mutant and BRCA2-mutant cancers, with no responses in tumors wild-type for BRCA." (PMID 23802008, 2013). "For example, BRCA2 functions in RAD51 loading and BRCA1 in countering 53BP1-mediated blocking of homologous recombinational (HR)-DNA repair; hence poly (ADP-ribose) polymerase (PARP) inhibitors have been developed and trialled against BRCA-driven cancers." (PMID 24286369, 2013). "In summary, our findings show that RAD21 expression is associated with a poorer prognosis in BRCA2 and BRCAX, but not in BRCA1 cancers." (PMID 22537934, 2012). "Because increased RAD21 expression may confer resistance to DNA-damaging agents, alternative treatment strategies may be useful in RAD21-positive BRCA2 and BRCAX cancers." (PMID 22537934, 2012). "Because BRCA1 and BRCA2 are involved in homologous recombination (HR)-based DSB repair, the elevated frequency of microhomology-mediated indels in BRCA1 or BRCA2 mutant cancers presumably reflects usage of alternative methods of DSB repair in these cancers." (PMID 22608084, 2012). "Thus, G2/M checkpoint regulators like CtIP, BRCA2 and PALB2 are potential targets for cancer therapy." (PMID 24970150, 2012). "Two individual cancer genomes analyzed by aCGH are shown to illustrate lack of deletion events affecting the BRCA2 gene locus at 13q13.1 in the TNP subtype of BRCA2 tumors." (PMID 21958427, 2011).